U6 (U6 spliceosomal RNA )
Gene: Small nuclear RNA gene on chromosome 1 (247,607,126 to 247,607,201, reverse strand). Ensembl gene ENSG00000283369.
Gene Ontology:
Molecular function: U4 snRNA binding
Biological process: formation of quadruple SL/U4/U5/U6 snRNP; spliceosomal tri-snRNP complex assembly
Cellular component: U4/U6 x U5 tri-snRNP complex; U6 snRNP
Homologues: Orthologues: chimpanzee U6 (99% identical), mouse Gm23535 (66% identical), rat LOC120096464 (64% identical). Paralogues in human: RNU6-1050P (83% identical), RNU6-1311P (82% identical), RNU6-333P (82% identical), RNU6-1048P (80% identical), RNU6-1060P (80% identical), RNU6-1172P (80% identical), RNU6-185P (80% identical), RNU6-24P (80% identical), RNU6-38P (80% identical), RNU6-455P (80% identical), RNU6-698P (80% identical), RNU6-829P (80% identical), and 1286 more.